HNF4A (hepatocyte nuclear factor 4 alpha)
Diseases named in the same sentence as HNF4A in open-access papers (continued):
Sharing a sentence is not in itself a finding about the gene and the disease.
prostate carcinoma (12 papers, 2009 to 2025). A carcinoma that arises from epithelial cells of the prostate gland. "Furthermore, treatment with a senescence inducer Dox could induce concomitant increased mRNA expressions of both HNF4α and p21 in LNCaP and PC-3 cells, suggesting a direct association between two factors in prostate cancer cells." (PMID 31695151, 2020). "For example, the overexpression of HNF4α induced p21 in prostate cancer cells, and the results of several experiments, including ChIP assays, suggest that this response is due to HNF4α interactions with distal (−980 to −755) response elements." (PMID 39858066, 2025). "The tumor-suppressor role of HNF4α through the regulation of p21-mediated cellular senescence in prostate cancer is also reported." (PMID 39199690, 2024). "Our results showed that HNF4α exhibited a reduced expression pattern in clinical prostate cancer tissues, prostate cancer cell lines and xenograft model of castration-relapse prostate cancer." (PMID 31695151, 2020). "Together, these results showed that HNF4α exhibited a downregulation in prostate cancer and also its advanced progression." (PMID 31695151, 2020). "Results showed that HNF4α expression was rescued in prostate cancer cells upon 5-aza-dC treatment, along with demethylation of the HNF4A promoter." (PMID 31695151, 2020). "Immunocytochemical staining also validated that HNF4α exhibited a decrease expression pattern in prostate cancer cells (LNCaP and PC-3) as compare with immortalized epithelial cells PWR-1E and nonprostatic BPH-1." (PMID 31695151, 2020). "We also characterized that the HNF4α-induced inhibition of cell proliferation and cell-cycle arrest in prostate cancer cells was mediated by a mechanism of its direct transactivation of CDKN1A (p21WAF1/CIP1) gene." (PMID 31695151, 2020). "To further validate the tumor-suppressing role of HNF4α in prostate cancer cell growth, we next generated stable HNF4α-transduced infectants in AR-negative PC-3 and AR-positive LNCaP cells for growth phenotype characterization." (PMID 31695151, 2020). "In vitro cell proliferation assay showed that contrary to shHNF4α infectants, all the immunoblot-validated HNF4α-infectants of prostate cancer cells proliferated at slower rates than their empty vector-infectants." (PMID 31695151, 2020). "In summary, the current study provides evidence showing that the druggable NR HNF4α performs a tumor suppressor function in prostate cancer, by suppressing cellular senescence via its transactivation of CDKN1A." (PMID 31695151, 2020). "In this study, we characterized the functional significance of HNF4α in the growth regulation of prostate cancer." (PMID 31695151, 2020). "To further elucidate the role of HNF4α in the growth suppression of prostate cancer cells, we next analyzed the cell-cycle progression status of HNF4α-infectants by DNA flow cytometry." (PMID 31695151, 2020). "Both datasets confirmed that the prostate cancer samples exhibited a lower expression of HNF4α as compared with normal prostate gland or BPH." (PMID 31695151, 2020). "We hypothesized that FOXA1 was the PF for HNF4G (and possibly HNF4A), as seen with other NRs in breast and prostate cancer that require FOXA1." (PMID 41168397, 2025). "However, one report indicated HNF4α as a tumor suppressor of prostate cancer by promoting p21-driven senescence." (PMID 36249028, 2022). "It has been revealed that HNF4α-mediated AMPK/mTOR pathway promotes prostate cancer progression." (PMID 36249028, 2022). "Our study also suggests that targeting of HNF4α signaling could be a potential therapeutic strategy for cellular senescence in prostate cancer." (PMID 31695151, 2020).
prostate carcinoma (continued). "Expression analysis of HNF4α in a castration-resistant prostate cancer (CRPC) xenograft model VCaP-CRPC showed that HNF4α displayed a significant decreased expression in castration-relapse VCaP-CRPC xenograft tumors as compared with precastrated VCaP xenograft tumors." (PMID 31695151, 2020). "Our results indicate that HNF4α could perform a tumor suppressor function in cell-cycle regulation in prostate cancer cells." (PMID 31695151, 2020). "Together, these findings showed that overexpression of HNF4α could induce cell-cycle arrest and cellular senescence in prostate cancer cells, resulted in their growth suppression." (PMID 31695151, 2020). "We next sought to determine the downstream molecular targets of HNF4α that could mediate the induction of cellular senescence in HNF4α-infectants of prostate cancer cells." (PMID 31695151, 2020). "We next investigated whether epigenetic events would be involved in the decreased expression of HNF4α in prostate cancer cells." (PMID 31695151, 2020). "We showed that HNF4α, which exhibited a downregulation expression in prostate cancer, could suppress the malignant growth of prostate cancer cells via its direct transcriptional regulation of senescence-regulatory gene CDKN1A (p21WAF1/CIP1)." (PMID 31695151, 2020). "Together, these results showed that knockdown of endogenous HNF4α could promote both in vitro and in vivo malignant growth capacities of prostate cancer cells." (PMID 31695151, 2020). "In this study, we determined the functional significance of HNF4α in prostate cancer." (PMID 31695151, 2020). "Stable HNF4α knockdown not only could promote cell proliferation and suppress doxorubicin (Dox)-induced cellular senescence in prostate cancer cells, but also confer resistance to paclitaxel treatment and enhance colony formation capacity and in vivo tumorigenicity of prostate cancer cells." (PMID 31695151, 2020). "A previous study showed that selenium-binding protein 1(SBP1) inhibits prostate cancer growth by reducing oxygen consumption and increasing the activation AMPK, and that HNF4α binds to the promoter of SBP1 to restrain SBP1 transcription." (PMID 36249028, 2022). "Similarly, to clarify whether promoter methylation would also contribute to the HNF4α silencing, we treated prostate cancer cells (PC-3, LNCaP, and ARCaPM) with a DNA methyltransferase inhibitor 5-aza-2′-deoxycytidine (5-aza-dC), followed by quantitative methylation-specific PCR (qMSP) analysis." (PMID 31695151, 2020). "In the colon cfDNA pool, TFs EVX2, DLX2, HNF1A, HNF4A, and HNF4G and TFs AR and HOXB13 in the prostate cancer cfDNA pool had increased accessibilities, whereas FOXA1 exceeded the >5 z-score threshold in both the prostate and breast pool." (PMID 31604930, 2019). "Results of qRT-PCR showed that ectopic HNF4α overexpression induced no significant changes in PTEN transcript levels in prostate cancer cells." (PMID 31695151, 2020). "Since HNF4α displayed a decreased expression pattern in prostate cancer tissues and models of prostate cancer, we hypothesize that HNF4α might perform a negative or tumor-suppressing function in prostate cancer." (PMID 31695151, 2020). "However, the exact functional roles of HNF4α in prostate cancer progression are still not fully understood." (PMID 31695151, 2020).
prostate carcinoma (continued). "We found that in vitro treatment with a histone deacetylase inhibitor trichostatin A (TSA) could significantly increase the HNF4α expression in an androgen receptor (AR)-negative (PC-3) and two AR-positive (LNCaP, ARCaPM) prostate cancer cell lines in a time-dependent manner." (PMID 31695151, 2020). "Intriguingly, we also observed that knockdown of HNF4α could enhance the expression of AR and its variant AR45, and functionally promote the resistance to androgen-deprivation in vitro and in vivo in LNCaP prostate cancer cells (data not shown)." (PMID 31695151, 2020).
Fanconi syndrome (11 papers, 2018 to 2024). "Biallelic variants in HNF1A can cause hepatocellular adenomas, while variants in HNF4A can cause Fanconi renotubular syndrome and are associated with SHBG levels." (PMID 39666780, 2024). "Gene analysis showed a heterozygous p.R63W mutation in the HNF4A gene that is responsible for Fanconi syndrome and hyperinsulinemic hypoglycemia." (PMID 30005691, 2018). "We report the case of a patient with Fanconi syndrome and hyperinsulinemic hypoglycemia caused by the mutation of HNF4A presenting with additional auditory phenotypes." (PMID 30005691, 2018). "Recently, patients with congenital hyperinsulinism and Fanconi syndrome due to the p.R63W mutation in HNF4A have been described." (PMID 30005691, 2018). "Defective proximal tubule function causes Fanconi syndrome and the adult-onset knockout of Hnf4a could be used to study Fanconi syndrome." (PMID 34001900, 2021). "In conclusion, hearing loss may be found in children with HNF4A-related Fanconi syndrome, and auditory function should be assessed." (PMID 30005691, 2018). "Genetic analysis of Case 3 showed a missense mutation located in exon 2 of HNF4A gene [EF591040.1; c.253C > T; p.R85W] which is responsible for Fanconi syndrome." (PMID 33430795, 2021). "Additionally, Fanconi renotubular syndrome is a unique phenotype comprising both MODY1 and atypical Fanconi syndrome, which occurs due to a heterozygous missense mutation, R76W in HNF4α." (PMID 37635981, 2023). "Importantly, our study demonstrates compromised proximal tubules and impaired reabsorption in an adult-onset knockout of HNF4A, recapitulating Fanconi syndrome." (PMID 34001900, 2021). "Sanger DNA sequencing revealed a missense mutation located in exon 2 of HNF4A gene [EF591040.1; c.253C > T; p.R85W] (pathogenic, Fanconi syndrome, autosomal dominant) (his parents did not carry the same variant), and he was diagnosed as Fanconi syndrome." (PMID 33430795, 2021).
non-alcoholic steatohepatitis (11 papers, 2017 to 2025). "In non-alcoholic steatohepatitis and high-fat diet-fed diabetic models, liver expression of HNF4-α is significantly reduced." (PMID 39524892, 2024). "Acetylation of HNF4α was shown to be altered in human decompensated hepatocytes from nonalcoholic steatohepatitis (NASH) and alcohol-mediated Laennec’s cirrhotic explanted livers." (PMID 37404310, 2023). "This loss of liver identity with Hnf4a deletion echoes observations in models of non-alcoholic steatohepatitis where, interestingly, ATAC-seq analyses indicate loss of HNF4A activity." (PMID 35443180, 2022). "HNF4α plays a significant role in lowering inflammation, and the reduced expression of HNF4α was observed in alcoholic and nonalcoholic steatohepatitis patients." (PMID 35723304, 2022). "Evidence has supported the role of HNF4α in controlling lipid metabolism and inflammation in patients using knockout animal models of alcoholic or nonalcoholic steatohepatitis." (PMID 35723304, 2022). "Increased miR-34a expression, which was paralleled to the increased TG accumulation, was detected in patients with nonalcoholic steatohepatitis and mice fed a high-fat diet as a result of inhibited hepatocyte nuclear factor 4 alpha (HNF4α) expression in both human and mouse hepatocytes." (PMID 31500376, 2019).
renal cell carcinoma (11 papers, 2011 to 2025). "Moreover, it was reported in a prior research that HNF4A deficiency diminished renal cell carcinoma cell proliferation, migration and invasion." (PMID 34586697, 2021). "Decreased expression of HNF4A has been shown in renal cell carcinoma and has recently been shown to regulate key genes involved in cellular proliferation." (PMID 23671415, 2013). "In addition, human renal cell carcinomas (RCC) show a 4.7 fold downregulation in HNF4A mRNA level and the abundance as well as DNA binding activity of its protein is frequently reduced in tumors compared to normal tissue." (PMID 22140441, 2011).
Sepsis (11 papers, 2016 to 2025). Sepsis is defined as life-threatening organ dysfunction caused by a dysregulated host response to infection. "In conclusion, these findings suggest that the loss of HNF4α and PPARα function during sepsis disrupts Nr1i3 transcription, thereby impairing CAR activity." (PMID 40904458, 2025). "Sepsis induces progressive hepatic loss of HNF4α function, and the HNF4α agonist NCT protects against sepsis independently of bacterial load, highlighting HNF4α’s critical role in sepsis tolerance." (PMID 40920830, 2025). "An interesting nuclear receptor, whose expression is mainly regulated by HNF4α and has barely been investigated in sepsis, is the constitutive androstane receptor (CAR), encoded by the Nr1i3 gene." (PMID 40904458, 2025). "In conclusion, hepatic HNF4α activity is decreased during sepsis, causing PPARα downregulation, metabolic problems, and a disturbed IL6-mediated acute phase response." (PMID 39261648, 2024). "We found that sepsis causes a progressive hepatic loss-of-function of HNF4α, which has a strong impact on the expression of several important nuclear receptors, including PPARα." (PMID 39261648, 2024). "In the current paper, we show that HNF4α loses its function in liver during sepsis, and that this loss-of-function is responsible for the PPARα-mediated problems we observed previously, as well as many others." (PMID 39261648, 2024). "Our data identify an HNF4α loss-of-function (LOF) in mouse liver during sepsis, as observed in chronic liver diseases such as NAFLD and alcoholic hepatitis (AH)." (PMID 39261648, 2024). "This study shows that loss of hepatic HNF4α activity in sepsis disrupts PPARα-regulated lipid metabolism and the acute phase response, both of which can be restored by the agonist NCT." (PMID 39261648, 2024). "Recently, it was demonstrated that PPARα mRNA and protein levels are downregulated upon sepsis due to HNF4α loss of function." (PMID 39456859, 2024). "The regulatory axis of HNF4A/NCOA2/GR/STAB1 could potentially serve as a therapeutic target for sepsis-associated lung damage." (PMID 39979267, 2025). "Although HNF4α loss-of-function in sepsis affects the chromatin state, PPARα activity, lipid metabolism, and the APR, its impact on the activity of other nuclear receptors remains unclear." (PMID 40904458, 2025). "Consequently, these findings indicate that the loss of HNF4α function during sepsis not only decreases Nr1i3 mRNA expression, but also reduces chromatin accessibility at CAR binding sites, thereby contributing to its impaired DNA binding in CLP." (PMID 40904458, 2025). "The progressive loss of HNF4α activity in sepsis is associated with diminished chromatin binding of HNF4α, thereby reducing H3K27 acetylation and chromatin accessibility and causing the downregulation of many genes coding for proteins, among which nuclear receptors such as PPARα." (PMID 40904458, 2025). "However, ChIP-qPCR analysis demonstrated a diminished association of HNF4α with the promoter region of Ppara during sepsis." (PMID 39261648, 2024). "Therefore, we believe that both the lipid-associated problems and the reduced acute phase response downstream of HNF4α loss-of-function contribute to lethality in sepsis." (PMID 39261648, 2024). "Finally, we confirm hepatic HNF4α loss-of-function in septic pigs and a humanized liver mouse sepsis model, enhancing the translatability of the current findings." (PMID 39261648, 2024). "A critical role for HNF4α in polymicrobial sepsis-associated metabolic reprogramming and death." (PMID 39261648, 2024). "To explore the epigenetic alterations underlying the changes in HNF4α chromatin binding during sepsis, we analyzed the liver 8 h after sham or CLP with ‘Assay for transposase-accessible chromatin using sequencing’ (ATAC-Seq), as well as ChIP-Seq for H3K4me3 and H3K27ac." (PMID 39261648, 2024).